TNF (tumor necrosis factor)
Diseases named in the same sentence as TNF in open-access papers (continued):
Sharing a sentence is not in itself a finding about the gene and the disease.
autism (86 papers, 2011 to 2025). Persistent deficits in social interaction and communication and interaction as well as a markedly restricted repertoire of activity and interest as well as repetitive patterns of behavior. "Disruptions in the cytokine network, including increased TNF-alpha levels, have been associated with neurodevelopmental abnormalities and behavioral symptoms in autism." (PMID 39337983, 2024). "TNF-alpha: For TNF-alpha, our findings revealed significant results that suggest the potential involvement of TNF-alpha in the inflammatory processes associated with autism symptoms." (PMID 39337983, 2024). "Several studies, including both epidemiological research and animal models, have suggested an association between TNFα and autism." (PMID 37290815, 2023). "Biomarkers linked to autism and/or pioglitazone were also studied to attempt to understand the mechanisms involved, namely, IL-6, TNF-alpha, MCP-1, insulin, and leptin." (PMID 29791472, 2018). "Neuroimmune biomarkers linked to autism and/or pioglitazone, namely, IL-6, tumor necrosis factor (TNF)-alpha, monocyte chemotactic protein (MCP)-1/CCL2, insulin, and leptin, were also studied." (PMID 29791472, 2018). "There is evidence that an increase of TNF-α is associated with stereotypic behaviors similar to those found in individuals with autism." (PMID 26441683, 2015). "Thus it can be inferred that TNF-α-mediated inflammation is a candidate for causing lower levels of MS mRNA in autism." (PMID 23437274, 2013). "The convergent cytokine profiles between Long COVID and autism, particularly sustained elevation of IL-6 and TNF-α with concurrent IL-10 deficiency, provide biological plausibility for shared pathogenic mechanisms that could affect neurodevelopment through neuroinflammation." (PMID 40843696, 2025). "The inflammatory profile in autism is marked by an abundance of pro-inflammatory mediators, such as increased levels of IL-1β, IL-6, IL-8, TNF-α, and interferon-γ." (PMID 41425587, 2025). "In various studies, TNF‐α, IL‐1β, and IL‐6 levels were found to be higher in autism groups compared to controls." (PMID 39401991, 2025). "Studies have shown that patients with autism have increased levels of TNF-α and reduced expression of tumor necrosis factor α-regulated long noncoding RNA (THRIL) in their serum." (PMID 38255315, 2024). "Further research with larger cohorts is warranted to conclusively determine the implications of CXCL8, IL-6, and TNF-alpha in early childhood autism." (PMID 39337983, 2024). "In this study, the autism-induced group showed a considerable rise in the proinflammatory marker TNF alpha in the hippocampal region as compared to the control group." (PMID 38344592, 2024). "Further statistical analysis of the mean values of TNF-alpha serum concentrations within the autism and control groups revealed significant differences between age groups using the Tukey HSD test (significance p < 0.05)." (PMID 39337983, 2024). "Within the autism group, a Student’s t-test for equal variances showed statistical significance, indicating that children with autism aged <5 years had higher TNF-alpha values than those >5 years." (PMID 39337983, 2024). "Specifically, 40% of children with autism under 5 years had elevated TNF-alpha levels compared to their older counterparts." (PMID 39337983, 2024). "Studies have reported increased levels of TNF-alpha in children with autism, particularly those with gastrointestinal symptoms." (PMID 39337983, 2024). "TNF was related to autism, and TNF high blood concentration was observed in autistic children associated with symptom severity." (PMID 36691005, 2023). "TNF-α levels correlated positively with autism severity, and decreased expression of immunoregulatory genes is related to TNF-α." (PMID 36899877, 2023). "Previous studies have shown that high levels of IL-6, TNF-α, and IL-1β are correlated with the severity of autism symptoms, which include stereotypical behaviors and impaired communication skills." (PMID 36268027, 2022).
autism (continued). "We found that compared with controls, in subjects with autism, cytokines IL-6, IL-17, TNF-α, and IL-1β increased in the plasma and serum." (PMID 36268027, 2022). "In this review, we found that IL-6, IL-17, TNF-α, and IL-1β were increased in the in the serum but unchanged in the plasma in subjects with autism." (PMID 36268027, 2022). "Elevated IL-6 levels have been described in monocytes and neutrophils at both baseline and after in vitro stimulation in autism, whereas augmented TNF-α levels have been described only in the post-stimulated monocytes of individuals with autism." (PMID 36268027, 2022). "Altogether, we suggest that monocytes are the predominant cells contributing to the elevated cytokine levels of IL-6, TNF-α, and IL-1β in autism, along with CD4+ T cells, which act as another source of IL-1β, whereas neutrophils are another source of IL-6." (PMID 36268027, 2022). "The down-regulation of MMP-9 in the brain of PPA-induced autism-like rats is unexpected because elevated brain MMP-9 levels after PPA exposure amplify neuroinflammation by activating TNF-α and other pro-inflammatory markers and promote autistic-like features." (PMID 35334937, 2022). "In this review, we found elevated levels of IL-6, TNF-α, and IL-1β in the plasma/serum of individuals with autism." (PMID 36268027, 2022). "Neuroinflammation is one of the characteristic features of autism; elevated levels of interleukin‐6 (IL‐6) and tumor necrosis factor (TNF) are also detected in the serum of affected individuals." (PMID 37786737, 2022). "In our previous study, we found that the levels of TNF-α and interleukin-6 were significantly increased in children with autism." (PMID 35002603, 2021). "Of these biomarkers, autism has a link to tumor necrosis factor-alpha (TNF-α), interleukin 8 (IL-8), interleukin 6 (IL-6)." (PMID 33269154, 2020). "Five already reported autism associated pro-inflammatory cytokines [interferon-γ (IFN-γ), interleukin-1β (IL-1β), IL-6, IL-12, and tumor necrosis factor-α (TNF-α)] were detected in plasma by enzyme-linked immunosorbent assay (ELISA) analysis." (PMID 30941018, 2019). "The myeloid dendritic cells, which produce among others TNF- α and IL-6, have been associated with increased GI symptoms in ASD as well as increased amygdalar volume and regressive autism." (PMID 31835709, 2019). "TNF-α in sera of 32 ASD children was found to be over-produced in another study; also in this further case, TNF-α levels were positively correlated with the ASD severity (as tested by Autism Behavior Checklist, ABC), likely indicating an ASD phenotype." (PMID 29867038, 2018). "A relevant point to be considered in the neuroimmune interactions occurring in autism is the fact that the intestinal mucosa of children with autism has a higher frequency of TNF-α+ T cells and lower frequency of IL-10+ T cells." (PMID 26441683, 2015). "Elevated CSF TNF-α in autistic subjects prompted our examination of a possible role for this proinflammatory cytokine in decreasing MS mRNA in autism." (PMID 23437274, 2013). "MS mRNA levels were significantly lower in autistic subjects, especially at younger ages, and this decrease was replicated in cultured human neuronal cells by treatment with TNF-α, whose CSF levels are elevated in autism." (PMID 23437274, 2013). "The purpose of this phase 2 pilot study is to determine the safety and pharmacodynamics of lenalidomide in children with autism who have elevated TNF-α levels." (PMID 22997574, 2012). "Only one study looking at cytokine levels in CSF and serum in autism has been completed that describes an elevated TNF-α ratio of the cerebrospinal fluid levels to serum levels." (PMID 22997574, 2012). "This pilot study evaluated lenalidomide at reduction of TNF-α and improvement of behavior and language in children with autism with elevated TNF-α." (PMID 22997574, 2012).
autism (continued). "Larger blinded and placebo-controlled studies assessing cytokine measurement and cytokine-targeted treatment in autism patients with TNF-α or other inflammatory cytokine elevation are warranted." (PMID 22997574, 2012). "This study suggests that the oral TNF-α inhibiting agent lenalidomide is a potential novel mechanism for treatment of autism with regression in the presence of elevated TNF-α markers in CSF and serum." (PMID 22997574, 2012). "Similarly, MOD significantly reduced IL-17, IL-2, TNF-α, and NF-KB levels in the propionic acid rat model of autism‐like behavior." (PMID 40234306, 2025). "In rat models of autism induced by propanoic acid, resveratrol administered at doses of 5, 10, and 15 mg/kg for four weeks was shown to improve behavioral deficits and reduce brain levels of pro-inflammatory cytokines, including TNF-α and IL-6." (PMID 41155624, 2025). "Children with attention deficit hyperactivity disorder demonstrate interleukin-6 levels ranging from 3.1 to 6.2 picograms per milliliter with tumor necrosis factor-alpha between 6 and 15 picograms per milliliter, representing intermediate elevation compared to autism profiles." (PMID 40843696, 2025). "Moreover, insulin exhibited noteworthy capabilities in decreasing brain MDA, IL-2, IL-17, and TNF-α levels within autism models." (PMID 39329976, 2024). "Notably, some children with autism show behavioral improvements during fever-induced inflammation, highlighting the potential role of TNF-alpha in autism severity." (PMID 39337983, 2024). "Several studies indicate that individuals with autism may have an immune system dysfunction in the CNS, leading to elevated cytokine levels such as TNF-α, IL1.β, and IL-6." (PMID 39720795, 2024). "Moreover, elevated levels of TNFα have been observed in a mouse model of autism induced by prenatal exposure to valproic acid, suggesting a potential contribution of TNFα to autism in mice." (PMID 37290815, 2023). "The measured cytokine production against common dietary proteins in autism showed an increase of pro-inflammatory cytokine responses (IFN-γ and TNF-α) as a factor of susceptibility to predispose autistic children to GI inflammation and produce a worsening of disorder behavioral symptoms." (PMID 35328471, 2022). "Indeed, overexpression of TNF-α, IL-6, and IL-17 genes observed in the brain of patients with autism seriously impaired the dendritic spine development and promoted autistic-like features." (PMID 35334937, 2022). "The current study demonstrated that PPA-induced autism in rats was characterized by a significant increase in the expression of TNF-α, IL-6, IL-17, CCL-3, CCL-5, and CXCL-16 levels as a down-regulation of OPG in the brain of PPA-induced autism-like rats, compared to the control animals." (PMID 35334937, 2022). "They revealed an increase in the plasma levels of TNF-α, IL-8, and IL-6 might be partially responsible for developing autism." (PMID 33269154, 2020). "We reasoned that abnormal embryonic neurogenesis and autism‐related phenotype in STINGcKO mice could be rescued by TNF‐α." (PMID 33304758, 2020). "Moreover, it is well known that multiple neuro-inflammatory mediators, which are involved in the etiology of autism, are usually released in response to IL-1 α; these mediators include IL-6, TNF- α, prostaglandins, and cyclooxygenase-2." (PMID 31733650, 2019). "Activation of astrocytes and the subsequent pro-inflammatory cytokines release, including interleukin 6 (IL-6), tumor necrosis factor alpha (TNFα), and interleukin 1B (IL-1B), has also been observed in autism within the brain as well as peripherally in the cerebrospinal fluid." (PMID 29234492, 2017). "Microglial abnormality could result from CNS or peripheral immune signals, such as auto-antibodies, or by peripheral chemokines/cytokines (such as IL-1β, IL-6 and TNF-α) up-regulated in autism." (PMID 28367116, 2017).
autism (continued). "Our results suggest that TNF-α might affect the progress of autism through another pathway, such as the MAPK/JNK pathway." (PMID 25729218, 2015). "Moreover, levels of inflammation-associated cytokines such as tumor necrosis factor-alpha (TNF-α) are significantly elevated in CSF and postmortem brain samples from autistic subjects, which suggests that cortical MS status might be altered by oxidative stress in autism." (PMID 23437274, 2013). "While ADAM17 itself has not been specifically studied in association with autism, the cerebrospinal fluid to serum ratio for TNF-α is elevated in subjects with autism compared to other pathological states." (PMID 23801940, 2013). "Lower ADA activity in patients with autism might also be related to the increased levels of interleukin-6 and tumor necrosis factor-α, and the impaired Ca2+ and K+ homeostasis that were reported from two studies using the same investigated autistic samples." (PMID 22958401, 2012). "Thus, whether TNFα and its related pathways are involved in hippocampal-dependent behaviors in addition to autism-specific behavior should be investigated in future work." (PMID 37290815, 2023). "It is not yet clear if the abnormal level of TNF-α is due to pro-inflammatory conditions or to disturbed associated signaling that takes place throughout the pathogenesis of autism, such as the reported down regulation of ADAM17, which is as a TNF converting enzyme." (PMID 37371450, 2023). "Indeed, the levels of TNFα in the Xie autism group showed a tendency toward significance (p: 0.07)." (PMID 30320048, 2018). "Our results provide further support for altered innate immunity being an important autism pathogenic factor, with autistic children showing increased blood TNF-α concentrations associated with symptom severity, and decreased expression of the THRIL gene involved in regulating TNF-α." (PMID 29137272, 2017). "The unexpected elevation of HSP70 could be related to the etiology of autism by considering the fact that HSP70 initiates TNF-mediated apoptosis by binding IκB kinase (IKK) and impairing nuclear factor-kappaB (NF-κB) survival signaling due its inactivation after being phosphorylated." (PMID 23231720, 2012). "Similarly, in rats with propionic acid (PPA)-induced autism, daily treatment with curcumin at doses of 50, 100, and 200 mg/kg for four weeks improved behavioral performance while alleviating oxidative–nitrosative stress, mitochondrial dysfunction, and the elevation of TNF-α and MMP-9." (PMID 41155624, 2025). "The activation of astrocytes and microglia in the cortex and cerebellum leads to the increased expression of IL-6, TNF-α, and MCP-1 in different brain regions of individuals with autism." (PMID 39065682, 2024). "Increased levels of pro-inflammatory cytokines, such as interleukin-17 A (IL-17 A), tumor necrosis factor-alpha (TNF-alpha), and interleukin-1 beta (IL-1β), have been observed in the blood and cerebrospinal fluid of individuals with autism." (PMID 38475688, 2024). "The proinflammatory markers TNF alpha, transforming growth factor (TGF) beta-1, interleukin (IL) 6, and IL-1 beta were significantly elevated in the autism-induced group compared to the control group." (PMID 38344592, 2024). "Compellingly, proinflammatory cytokines, including tumor necrosis factor-alpha (TNF-α), interleukin-6 (IL-6), IFN-γ, have exhibited significant upregulation in the brains of individuals with autism." (PMID 37815997, 2023). "Collectively, we found increased levels of IL-6, IL-17, TNF-α, IL-1β, IFN-γ, RANTES, and IL-8 in the plasma/serum in autism, which is overall consistent with the findings from previous systematic reviews." (PMID 36268027, 2022). "Postmortem studies have demonstrated the presence of brain neuroinflammation in patients with autism, as shown by marked activation of astrocytes and microglia together with abnormal chemokine and cytokine levels, such as IL-6, IL-8, IFN-γ, TNF-α, and TGF-β1." (PMID 34193257, 2021).
autism (continued). "Comparison of the TNFα and soluble receptors (pg/ml) following cell culture in media alone or stimulation with PHA in children with autism (n = 36) and typically developing controls (n = 27)." (PMID 30524316, 2018). "The results showed that GM-CSF, TNF-α, and IL-13 production were significantly increased, whereas IL-12p40 was decreased following PHA stimulation in autism relative to TD controls." (PMID 25729218, 2015). "In some studies, biomarkers of inflammation or immune dysregulation have been correlated with ASD severity and an elevation in TNF-alpha has been reported in ASD lymphocytes and in amniotic fluid in children who develop autism." (PMID 24795645, 2014). "Levels of glutamate, GABA, glutamate/GABA, TNF-α, IL-6, IFN-γ and IFI16 were compared between patients with autism and age-matched control subjects." (PMID 25407263, 2014). "Relatedly, whole-genome DNA methylation analysis uncovered epigenetic dysregulation of several complement genes such as C1Q, C3, and ITGB2 (C3R), as well as several other inflammatory genes (e.g., TNF-α, IRF8, and SPI1) in postmortem brain samples of patients with autism." (PMID 37107654, 2023). "Interestingly, sodium valproate (an epigenetic drug that inhibits HDACs) decreases TNF-α and NOS2 expression levels, hinting at an opportunity for autism epigenetic therapy using HDAC inhibitors." (PMID 37107654, 2023). "Furthermore, stereotypic behavior, a core symptom of autism, seemed to correlate with down-regulation of TGF-β1 and GM-CSF, as well as up-regulation of IL-1β, IL-6, IL-8, IL12p40, TNF-α, and interferon (IFN)-γ." (PMID 35328471, 2022). "Although not statistically significant, levels of fecal TNFα were increased in children with autism, and a strong correlation between TNFα levels and GI symptoms was found, but, significantly increased levels of TNFα were also described." (PMID 36296284, 2022). "Our study also indicated that testosterone alone cannot induce TNF-α expression in the microglia, indicating that other hormones may be responsible for the link between CYP11A1 expression and autism." (PMID 35002603, 2021). "We speculate that TNFα, elevated in autism, favors increased p38 and JNK resulting in increased brain matter, while decreased TNFα promotes apoptosis via p38 and JNK in AD." (PMID 31024350, 2019). "It is still unclear whether the increased levels of TNF-α and other cytokines are a reflection of a pro-inflammatory status in ASD children or dysfunctional immune regulation occurring in autism pathogenesis." (PMID 29137272, 2017). "Such inflammatory cytokines include: interleukin-1beta, interleukin-6, interleukin-8, tumor necrosis factor alpha (TNF-alpha), and gamma-interferon (INF-gamma); and with many of these cytokines, the higher their concentrations, the more severe are the symptoms of autism." (PMID 26869906, 2016). "In contrast, the persistent inflammatory condition in autism may inhibit IL-38 expression via negative feedback processes involving pro-inflammatory cytokines such as TNF-α and IL-1β." (PMID 41425587, 2025). "Interestingly, the increase in IL-6, IL-17, TNF-α, and IL-1β in the serum was in accordance with the elevated levels of these cytokines in in vitro stimulated neutrophils, monocytes, and CD4+ T cells in individuals with autism, as compared with controls." (PMID 36268027, 2022). "The expression of IL-1β, IL-6, IL-17, and TNF inflammatory molecules is increased in the brain, cerebrospinal fluid, and serum of some patients with ASD, whereas NF-kB is activated in the brain, which then stimulates peripheral blood immune cells in patients with autism." (PMID 28808521, 2017). "Similarly, co-ultramicronized palmitoylethanolamide combined with the flavonoid luteolin effectively alleviated both social and non-social deficits in a murine autism model by modulating TNFα and IL-1β, reducing GFAP and NF-κB expression, and enhancing hippocampal neurogenesis and neuroplasticity." (PMID 41155624, 2025).